CD55 (CD55 molecule (Cromer blood group))
Diseases named in the same sentence as CD55 in open-access papers (continued):
Sharing a sentence is not in itself a finding about the gene and the disease.
bacterial infections (5 papers, 2012 to 2025). "CD55 is elevated on white cells in women experiencing preterm labor (a pathophysiology commonly associated with bacterial infection) and failure to maintain CD55 was associated with subsequent preterm delivery." (PMID 23152895, 2012). "For instance, coxsackievirus and other enteroviruses utilize Decay Accelerating Factor (DAF or CD55) as a receptor(PMID: 8764022), introducing hCD55 into TKO pigs (TKO/hCD55 clone pig) could potentially elevate the risk of viral and bacterial infections." (PMID 39902050, 2024). "As neutrophil influx is a major mechanism that counters bacterial infection in the gut, we tested whether StcE-mediated CD55 cleavage influenced the adhesion of human neutrophils to the apical surface of Caco-2 cells." (PMID 30190327, 2018).
adenocarcinoma (2 papers, 2017 to 2022). A common cancer characterized by the presence of malignant glandular cells. "We also conducted the stratified analysis by histological types of NSCLC and found that CD55 rs2564978 CC increased the risk of adenocarcinoma with OR (95% CI) of 1.35 (1.01–1.80)." (PMID 28008159, 2017). "We also conducted the stratified analysis by NSCLC histological types and found that CD55 rs2564978 CC increased the risk of adenocarcinoma with OR (95% CI) of 1.35 (1.01−1.80)." (PMID 28008159, 2017).
cardiovascular disease (2 papers, 2019 to 2023). "Statins, commonly used to treat cardiovascular diseases, have previously been shown to upregulate CD55 and CD59 expression in human umbilical vein endothelial cells." (PMID 37357314, 2023).
vasculopathy (1 paper, 2019). "Rapamycin upregulates expression of CD55 by inducing protein kinase Cα, AMP-activated kinase, and CREB-dependent pathways, thereby dampening allograft vasculopathy, a benefit that synergizes with statin therapy." (PMID 31555668, 2019).
CD55 also shares sentences with these, for which no sentence is quoted: atypical hemolytic-uremic syndrome (4 papers); neutropenia (3); acute myelogenous leukemia (2); acute renal failure (2); aplastic anemia (2); autoimmune thrombocytopenia (2); chronic obstructive pulmonary disease (2); glomerular disease (2); hantavirus infection (2); rectal cancer (2); type II diabetes (2); Acidosis (1); acute promyelocytic leukemia (1); acute respiratory distress syndrome (1); age-related macular degeneration (1); amnesia (1); angioedema (1); asthma (1); Atopic Dermatitis (1); autoimmune glomerulonephritis (1); bone marrow disease (1); C3 glomerulopathy (1); Cachexia (1); cavernoma (1); cervical tumours (1); Chagas disease (1); chronic granulomatous disease (1); colorectal adenocarcinoma (1); Coronary Artery Disease (1); cutaneous squamous cell carcinoma (1).
A further 63 diseases each share a sentence with CD55 in 1 paper.